HK2 (hexokinase 2)
Diseases named in the same sentence as HK2 in open-access papers (continued):
Sharing a sentence is not in itself a finding about the gene and the disease.
glioma (continued). "We then evaluated the expression of HK2 with the CGGA database and several clinical parameters in glioma patients." (PMID 35982398, 2022). "The intensity of HK2-positive staining in NOX2-positive staining and the number of cells showing subcellular co-localization of HK2 and NOX2 were increased in patients with G3 glioma (G3) relative to those in G1 and G2 gliomas (G1, G2)." (PMID 35158782, 2022). "MACC1-AS1 overexpression significantly enhances the level of HK2 and GLUT1, suggesting that MACC1-AS1 promotes glycolysis and leads to metabolic reprogramming in glioma progression." (PMID 34681857, 2021). "Our data firstly showed that the glycolysis process and the expression of glycolytic enzymes, HK-2 and PFKL) in glioma cells were suppressed upon the knockdown of UBE2D3." (PMID 34195079, 2021). "ZBTB4 bind to the HK2 and ACLY promoter regions and inhibit their transcription, thereby impairing glycolipid metabolism and proliferation of glioma cells." (PMID 34047477, 2021). "The results showed that expression levels of VEGFA, HK2, JUN, LDHA, and GAPDH were significantly high in glioma with wildtype-IDH and wildtype-1p/19q codeletion." (PMID 32500034, 2020). "We also measured protein expression levels of key glycolytic enzymes HK2 and LDHA in glioma cells, as well as enzyme activity of LDHA." (PMID 32774168, 2020). "Our results suggested that PERK played an important role on glioma carcinogenesis by regulation of AKT activation and subsequent HK2's mitochondria location." (PMID 25761777, 2015). "Resistance of gliomas to temozolomide may manifest due to alterations in the HOTAIR-miR125 signaling axis, via hyperactivation of hexokinase 2 (HK2)-mediated glycolytic pathway in tumor cells." (PMID 38366205, 2024). "Normal brain expresses HK1, but in glioma, an overexpression of HK2 has been reported; in fact, HK2 usually is expressed in skeletal and adipose tissue, but not in the brain." (PMID 38139462, 2023). "In contrast, treatment with the miR‐143‐3p mimic significantly inhibited HK2 expression regardless of overexpression of L1 in glioma cells." (PMID 36708044, 2023). "Also, it has been reported that the overexpression of HK2 in GBM patients correlated with an overall survival rate significantly lower compared to normal and low-grade glioma patients." (PMID 38139462, 2023). "Similarly, the number of cells showing subcellular co-localization of COL5A1 and HK2 was increased in patients with GBM (G4) and G3 glioma compared to that in G1 and G2 glioma." (PMID 35158782, 2022). "Moreover, it is noted that similar results were also determined by using western blot analyses that the inactivation of PI3K/Akt signalling pathways after HK2 knockdown in T98 and GBM1 glioma cells." (PMID 35982398, 2022). "Next, we examined whether NOX2 could regulate the expression of HK2, the first key enzyme in the glycolysis pathway, in U87MG glioma cells." (PMID 35158782, 2022). "Notably, compared with the adjacent normal tissue, further GEPIA analysis then confirmed that HK2 expression was significantly increased in LGG and GBM tissues and positively correlated with the malignancy of gliomas." (PMID 35982398, 2022). "Targeted biopsies revealed that the tissues with labels 7–10 showed high expression levels of hypoxia-inducible factor 1-alpha, glucose transporter 3, and hexokinase 2, which are typical of IDH wild-type glioma, whereas those with labels 1 showed low expression of these proteins." (PMID 35058510, 2022). "The identification of the downstream signals of HK2 demonstrated that the high expression of hub genes, including ITGB2, CD53, C3AR1, CYBB and ITGAM, maybe a potential target for the treatment of glioma." (PMID 35982398, 2022). "The intensity of HK2-positive staining and the number of cells that have subcellular co-localization of HK2 and NOX2 were elevated in patients with GBM (G4) and G3 glioma relative to those in patients with low-grade glioma (G1, G2)." (PMID 35158782, 2022).
glioma (continued). "Moreover, IDH1 wild-type gliomas displayed a significantly increased expression of glycolytic enzyme genes (LDHA, HK2, PGAM2, PGK1, PKM, TIGAR) compared to IDH1-mutant gliomas as shown in heatmaps." (PMID 33493139, 2021). "Consequently, in current study, we monitored HK2 and LDHA expression, as well as LDHA enzyme activity to analyze aerobic glycolysis of glioma cells." (PMID 32774168, 2020). "Although the mechanisms have not been explored in depth, JNK activation in glioma cells following chaetocin treatment led to a marked increase in PK activity and decrease of HK2 activity and expression, implying a role for the JNK pathway in restraining the glycolytic metabolism in glioma cells." (PMID 30487597, 2019). "“If HK2 is a direct functional downstream target of Bmi1” was not assessed, though a direct correlation was established between Bmi1 and HK2 expression in glioma cells." (PMID 29220380, 2017). "The IRS revealed a significant increase in HK2 expression in glioma samples compared to non-neoplastic brain tissue." (PMID 29220380, 2017). "Anaplastic astrocytoma (grade III) IDH1 mutant samples were significantly higher for HK2 expression and HK2 activity when compared to normal controls and grade II gliomas (*p < 0.05), but not significantly (ns) different from GBM and GBM cultures." (PMID 27588472, 2016). "The median survival of mice injected with HK2 KD glioma cells was significantly increased from 36 days to 48 days when compared to mice without HK2 knockdown (***p < 0.001)." (PMID 27588472, 2016). "Moreover, PERK silencing inhibited glioma cell viability and tumor growth by blocking AKT phosphorylation and consequently disrupting HK2's mitochondria translocation and glycolysis under low glucose metabolism stress." (PMID 25761777, 2015). "PERK silencing results in decreased glioma cell viability and ATP/lactate production upon low glucose stress, which is mediated by partially blocked AKT activation and subsequent inhibition of Hexokinase II (HK2)'s mitochondria translocation." (PMID 25761777, 2015). "Although there is no obvious difference of total HK2 expression, the HK2 expression in mitochondria strongly decreased in tumors formed by lenti-shRNA PERK glioma cells compared with lenti-NC gliomas." (PMID 25761777, 2015). "We selected seven glycolytic genes (HK2, PFKP, ALDOA, PGAM1, ENO1, ENO2 and PDK1) and confirmed their strong up-regulation under hypoxia by QPCR in seven GBM cell lines (five patient derived glioma stem-like cells and two adherent GBM cell lines)." (PMID 25932951, 2015). "This study suggests that Chr-A markedly reduces the expression levels of GLS, GDH1, HK2 and G6PD in U87 and U251 glioma cells, which support the significant metabolic pathways identified through AFADESI-MSI, suggesting that these key enzymes might be potential targets for Chr-A." (PMID 39330272, 2024). "In addition, the results indicated that miR‐143‐3p, which might directly target the 3'UTR of the hexokinase 2 (HK2) gene to regulate its protein expression, was subsequently involved in L1CAM‐mediated VM formation by glioma cells." (PMID 36708044, 2023). "To obtain further evidence that the miR‐143‐3p‐regulated HK2 is the downstream regulator of L1‐mediated VM formation and tumor invasion in glioma, we next detected HK2 expression in the L1‐overexpressing and control groups of different glioma cell lines with or without miR‐143‐3p mimic transfection." (PMID 36708044, 2023). "However, the potential immunological and clinical significance of HK2, especially in terms of prognostic prediction for patients with glioma, has not been fully elucidated." (PMID 35982398, 2022). "Notably, the levels of HK2 and the number of cells that have subcellular co-localization of HK2 and NOX2 were significantly increased in patients with GBM relative to those in G2 and G3 gliomas (G2, G3)." (PMID 35158782, 2022).
glioma (continued). "In the present study, we found that HK2 is highly expressed in gliomas and that HK2 expression is positively correlated with OS, PFS, and DSS in glioma patients, suggesting that it may be a potential clinical target for the treatment of glioma." (PMID 35982398, 2022). "Since high levels of HK2 lead to the high glycolytic phenotype in GBM, the quantification of miR-542-3p levels could be a prognosis marker for the high glycolysis metabolic phenotype of high-grade gliomas, including GBM." (PMID 33922649, 2021). "Tumor glycolytic enzymes hexokinase 2 (HK2), 6-phosphofructo-2-kinase/fructose-2,6-bisphosphatase (PFKFB3), pyruvate kinase M2 (PKM2), and lactate dehydrogenase 5 (LDH5) demonstrate increased activity in the glioma cells and supposed to be preferentially used by cancer cells." (PMID 34440090, 2021). "Furthermore, immunohistochemical staining showed that GLUT1, HK2, PKM2, LDH, and MCT1 were significantly downregulated in the 20(S)-Rg3 group, confirming that downregulation of NKILA by 20(S)-Rg3 reversed the Warburg effect in glioma cells in vivo." (PMID 32382013, 2020). "We also observed that silencing of circPOSTN could inhibit HK2 and LDHA expression in glioma cells." (PMID 32774168, 2020). "We detected the HK2 expression in glioma and non-neoplastic brain tissue samples by IHC." (PMID 29220380, 2017). "Similar to our HK2 protein results, primary GBM operative samples and GBM cultures had significantly higher hexokinase activity compared to normal controls (11 fold higher, (*p < 0.05)) and 6 fold higher (*p < 0.05) when compared to grade II gliomas (IDH1 mutant oligodendrogliomas) (p < 0.05)." (PMID 27588472, 2016). "Notably, according to the classification of central nervous system tumours divided adult gliomas based on IDH status and 1p19q codeletion status, similar results from TCGA and CGGA databases were also determined that the highest mRNA expression of HK2 was found in GBM." (PMID 35982398, 2022). "In addition, immunohistochemical staining showed that GLUT1, HK2, PKM2, LDH, and MCT1 were significantly downregulated in LN229-K.D.-NKILA group tumors, and also confirmed that decreasing the levels of NKILA inhibited the Warburg effect in glioma cells in vivo, consistent with the in vitro results." (PMID 32382013, 2020). "The effect of HK2 downregulation, both shRNA and miR-218 induced, on cellular metabolism (glycolytic activity), ATP synthesis, or FDG uptake of glioma cells was not addressed." (PMID 29220380, 2017). "In addition, the mRNA level of HK2 was always accompanied by poorer OS (P < 0.0001), PFS (P < 0.0001), and DSS (P < 0.0001) but not DFS (P = 0.19) in glioma patients." (PMID 35982398, 2022). "The rate-limiting, irreversible and glycolysis-related enzymes hexokinase (HK2 and HK3) and pyruvate kinase (PKM2), but not HK1 or the pyruvate kinase isoform PKLR, were also expressed at lower levels in IDH1MUT glioma compared with IDH1WT glioma." (PMID 28467784, 2017).
gastric cancer (71 papers, 2013 to 2026). A primary or metastatic malignant neoplasm involving the stomach. "This molecular competition impedes TRIM25-dependent K63-linked ubiquitination of HK2, thereby blocking its degradation and consequently promoting malignant proliferation in gastric cancer cells." (PMID 40796546, 2025). "Trastuzumab is the only approved treatment for HER2-positive gastric cancer, and its resistance is linked to hexokinase 2 (HK2)-controlled high-glucose enzymatic activity." (PMID 39011396, 2024). "HK2 plays significant roles in both the Warburg effect, a significant cause of relapse and pathogenesis in gastric cancer, and cancer cell immortalization." (PMID 36207306, 2022). "HK2 is abnormally expressed in a variety of cancers including gastric cancer, and the expression level of HK2 is closely associated with cancer prognosis and mortality." (PMID 34872447, 2021). "An important finding of the present study was that abnormally elevated NLRP12 expression during the progression of gastric cancer is strongly associated with the regulation of abnormal proliferation of gastric cancer cells through the ubiquitination of HK2 and subsequent HK2-mediated H3K18la." (PMID 40796546, 2025). "Mechanistically, NLRP12 binds to TRIM25 to prevent TRIM25 from participating in the K63-linked ubiquitination of HK2, which subsequently enhances the protein stability of HK2, thereby upregulating the expression of HK2 and promoting glycolysis in gastric cancer cells." (PMID 40796546, 2025). "Specifically, CagA expression is significantly elevated in 5-FU–resistant gastric cancer cells, along with increased expression of glycolytic enzymes such as hexokinase 2 (HK2) and lactate dehydrogenase A (LDHA)." (PMID 41220952, 2025). "SALL4 drives gastric cancer progression by regulating hexokinase II (HK2), further highlighting the role of glycolytic enzymes in tumor metabolism." (PMID 41220952, 2025). "IL-8 from gastric cancer mesenchymal stem cells (GCMSCs) facilitates HK2 translocation to the nucleus, where phosphorylated HK2 interacts with HIF-1α to promote PD-L1 transcription." (PMID 39897050, 2025). "First, HMGB2 boosts the transcriptional activity of HIF-1α, leading to upregulation of glycolytic enzymes such as LDHA, PKM2, and HK2, which help gastric cancer cells sustain glycolysis under hypoxic conditions." (PMID 41220952, 2025). "Conversely, on NLRP12 overexpression, the HK2 protein levels in gastric cancer cells significantly increased, whereas other glycolytic enzymes did not significantly change." (PMID 40796546, 2025). "Resveratrol reduces HK2 expression and lactate production, effectively inhibiting glycolysis and tumor growth in gastric cancer cells." (PMID 41220952, 2025). "In summary, the present study revealed that NLRP12-mediated HK2 ubiquitination is the main mechanism to regulate glycolysis and histone lactylation in gastric cancer and is important for the progression of this disease." (PMID 40796546, 2025). "Glucose and lactic acid metabolic reprogramming in gastric cancer cells largely depends on the protein stability of HK2." (PMID 40796546, 2025). "NLRP12 promoted the progression of gastric cancer mainly by promoting the metabolic reprogramming of gastric cancer cells, the expression of histone H3 lysine 18 lactylation (H3K18la) and the stabilization of hexokinase 2 (HK2), a crucial enzyme in glycolysis." (PMID 40796546, 2025). "To further clarify that NLRP12 promotes gastric cancer proliferation through HK2-mediated glycolysis, we employed both pharmacological inhibition (2-DG, a competitive HK2 inhibitor) and genetic silencing (shRNA-mediated HK2 knockdown)." (PMID 40796546, 2025). "Blocking the IL-8/CXCR2/HK2 axis effectively reduces PD-L1 expression and lactate production, enhancing the impact of anti-PD-1 therapy for advanced gastric cancer, with potential clinical benefits." (PMID 39897050, 2025).
gastric cancer (continued). "HGF produced by tumor mesenchymal stem cells increases HK2 expression in nearby gastric cancer cells, and HK2 plays an essential role in gastric cancer cell proliferation, migration, and gastric cancer progression." (PMID 41374996, 2025). "Previous studies have shown that gastric cancer cells have high glycolytic activity and high HK2 expression." (PMID 40796546, 2025). "In turn, the circular RNA derived from ribosomal protein S19 (circRPS19) upregulates USP7 expression, leading to an increase in HK2 protein levels and the promotion of aerobic glycolysis in gastric cancer cells." (PMID 39048965, 2024). "What’s more, the study showed that H. pylori virulence factor CagA contributed to 5-Fu resistance of gastric cancer cells through upregulating Hexokinase 2 (HK2) and LDHA-mediated glycolysis." (PMID 37328804, 2023). "Licochalcone A reduces the levels of Akt in two different types of gastric cancer cells to inhibit HK2-mediated tumor glycolysis." (PMID 37892405, 2023). "CircUBE2Q2 acts as a sponge for miR-370-3p, activating the STAT3 pathway to promote PFK and HK2 expression, thereby increasing glycolysis levels in gastric cancer cells and promoting cell proliferation and migration." (PMID 37599427, 2023). "circUBE2Q2 is significantly up-regulated in gastric cancer cells and promotes glycolysis by increasing the levels of HK2." (PMID 36438836, 2022). "Mechanistically, WTAP promotes the stability of hexokinase 2 (HK2) mRNA, a core molecule that regulates glucose metabolism, thus increasing glucose uptake in gastric cancer cells." (PMID 36139062, 2022). "In gastric cancer cell lines, 60 μM Lic A reduced the expression of HK2, decreased cell glucose consumption and lactic acid production, inhibited cell proliferation, and promoted apoptosis." (PMID 36438836, 2022). "N6-methyladenosine (m6A) is the most common RNA modifier in eukaryotes, and Wilms tumor 1 associated protein (WTAP) is an m6A methyltransferase that can enhance the stability of HK2 mRNA, thus promoting glycolysis in gastric cancer cases." (PMID 36438836, 2022). "Licochalcone A suppressed glycolysis and induced apoptosis in gastric cancer cells by inhibiting hexokinase 2 (HK2) and the AKT signaling pathway." (PMID 35082907, 2022). "After treatment with paeonol at 60 mg/L, the levels of GLUT1, LDHB, and HK2 proteins in gastric cancer cells decrease markedly, and aerobic glycolysis is significantly weakened." (PMID 36438836, 2022). "Our results demonstrated GCMSCs-derived HGF reprogramed glucose metabolism of gastric cancer cells by regulating HK2." (PMID 33718248, 2021). "HGF derived from GCMSCs promoted glycolysis, proliferation, and metastasis of gastric cancer by upregulating c-Myc-HK2 signal." (PMID 33718248, 2021). "Overall, the data obtained herein indicated that GCMSCs-derived HGF promoted gastric cancer progression by upregulating HK2 in vivo." (PMID 33718248, 2021). "HK-2, the first rate-limiting enzyme of glycolysis, can be modulated by miR-181b which has a binding site in the 3′-untranslated region of HK-2 transcript and found to be down-regulated in gastric cancer tissues." (PMID 34249759, 2021). "To further confirm that GCMSCs-derived HGF promoted tumor progression by upregulating HK2 in gastric cancer cells, we constructed a mouse tumor model." (PMID 33718248, 2021). "To further investigate the effect of HK2 induced by GCMSCs on gastric cancer cell proliferation, migration, and glucose metabolism, we analyzed the tumor cell processes." (PMID 33718248, 2021). "Taken together, these results suggest that SALL4 regulates the expression and activity of HK-2 in gastric cancer cells." (PMID 32489324, 2020). "SALL4 promoted the glycolysis of gastric cancer cells by activating the expression of HK-2, a key rate-limiting enzyme of glycolysis." (PMID 32489324, 2020).